RNU6-229P (RNA, U6 small nuclear 229, pseudogene)
Gene: Small nuclear RNA gene on chromosome 7 (69,401,202 to 69,401,303, reverse strand). Ensembl gene ENSG00000252423.
Homologues: Orthologues: chimpanzee U6 (100% identical), macaque U6 (90% identical). Paralogues in human: RNU6-38P (83% identical), RNU6-1145P (82% identical), RNU6-16P (81% identical), RNU6-393P (81% identical), RNU6-48P (81% identical), RNU6-85P (81% identical), RNU6-1029P (80% identical), RNU6-1214P (80% identical), RNU6-1316P (80% identical), RNU6-20P (80% identical), RNU6-333P (80% identical), RNU6-39P (80% identical), and 1288 more.